CBX6 (chromobox 6)
Diseases named in the same sentence as CBX6 in open-access papers (continued):
Sharing a sentence is not in itself a finding about the gene and the disease.
cancer (24 papers, 2013 to 2025). A tumor composed of atypical neoplastic, often pleomorphic cells that invade other tissues. "The consistent downregulation of CBX6 observed in our study supports previous pan-cancer analyses of CBX gene expression and prognosis." (PMID 40806514, 2025). "Eight members of the CBX clan, CBX1/2/3/4, were significantly expressed at a high level, whereas CBX6/7 was significantly downregulated in most cancer types, such as BLCA." (PMID 37189494, 2023). "Previous studies also found that the expression of CBX6 was significantly correlated with the infiltration of dendritic cells in carcinoma." (PMID 37428291, 2023). "The expression of CBX1, CBX2, CBX5, and CBX8 significantly positively correlates with cancer stemness in LIHC, LUAD, and UCEC tumors, while CBX6—negatively associates with cancer stemness in LUAD and PAAD tumors." (PMID 36361869, 2022). "Transcriptome analysis suggested that CBX6 regulates sets of genes involved in cancer cell migration and metastasis." (PMID 33028834, 2020). "Transcriptome analysis showed significantly altered expression of sets of genes, which has been known to regulate migration and metastasis of various cancers, in CBX-6 knockdown condition." (PMID 33028834, 2020). "We compared the mRNA expression of the CBXs in cancer and normal samples using the Oncomine database and found that the transcriptional levels of CBX1/2//3/4/5/8 were upregulated while that of CBX6/7 were downregulated in majority of the cancers." (PMID 33344640, 2020). "Given the significant correlation between CBX6expression levels and HCC clinical invasiveness, it is likely that CBX6 plays a positive role in cancer progression." (PMID 28122351, 2017). "CBX6 participates in mechanisms of chromatin regulation and is critical in cancer biology." (PMID 40175347, 2025). "The mechanism of CBX6 is complex in different types of cancers." (PMID 33344640, 2020). "The mRNA expression of CBX6 was lower in the cancer stages 1 and 4 compared to the normal tissues." (PMID 33344640, 2020). "However, in the STAD databases, the mRNA expression of CBX6 was significantly decreased, and the downregulation of the mRNA was associated with individual cancer stages 1 and 4 but of no significant correction with nodal metastatic status." (PMID 33344640, 2020). "Of note, It was revealed that the expression of most genes was generally consistent with results of TCGA cancer set, such as TRIM24, HMG20B, CBX6, IDH1, RCC1, RYBP, CBX7, and LBR." (PMID 36246611, 2022). "CBX paralogs are frequently misregulated in cancer, with CBX2 and CBX8 as the most commonly upregulated paralogs, and CBX7 and CBX6 as the most commonly downregulated." (PMID 34617019, 2021). "Of particular interest, our data revealed that expression of Chromobox 6 (CBX6), a component of PRC1, was suppressed in cancer specimens." (PMID 24260522, 2013). "CBX6 and CBX7 have been found to play contradictory roles in human cancers." (PMID 34395271, 2021). "Chromobox 6 (CBX6), one of the polycomb paralogs, functions in cancer progression." (PMID 34381502, 2021). "While many cancer-specific alterations in PcG subunits are related to specific developmental pathways or cancer-specific phenotypes, some sets of paralogs are universally up and downregulated across multiple cancers, including EZH2/EZH1, RING1B/RING1A and (CBX2/CBX8)/(CBX6/CBX7)." (PMID 34617019, 2021).
infection (2 papers, 2017 to 2022). The state of being infected such as from the introduction of a foreign agent such as serum, vaccine, antigenic substance or organism. "Only endogenous Cbx6 mRNA was efficiently downregulated by CBX6-shRNA infection, and all three cell lines showed similar levels of the ectopically expressed proteins, as determined by western blot." (PMID 29089522, 2017).
CBX6 also shares sentences with these, for which no sentence is quoted: benign mesothelioma (2 papers); diffuse intrinsic pontine glioma (1); gastrointestinal stromal tumor (1); lung adenocarcinoma (1); lung carcinoma (1); myelodysplastic syndrome (1); pancreatic adenocarcinoma (1); synovial sarcoma (1); urothelial carcinoma (1).